CD44 (CD44 molecule (IN blood group))
Diseases named in the same sentence as CD44 in open-access papers (continued):
Sharing a sentence is not in itself a finding about the gene and the disease.
breast carcinoma (continued). "CD44 is a cell-surface glycoprotein involved in cell-cell and cell extracellular matrix interactions including the migration and invasion of cancer cells and has been used as a key cancer stem cell-surface marker in various malignancies including breast cancer." (PMID 23401782, 2013). "Therefore, influence of CD44 gene polymorphisms in breast cancer treatment response to NACT is still not established." (PMID 23940692, 2013). "Consequently, high expression levels of CD44 may lead to a constitutive activation of STAT3 signaling in basal-type breast cancer." (PMID 23326564, 2013). "In support of this, a direct relationship between the co-expression of HIF-1α and the CD44+/CD24−/low phenotype has been observed by immunohistochemical analyses of 253 samples of breast ductal carcinoma from patients, and associated with a worse prognosis of breast cancer patients." (PMID 23301832, 2013). "Our study indicated that both the polymorphisms in CD44 gene might not have any effect on breast cancer risk prediction in north Indian population." (PMID 23940692, 2013). "Basal-like breast carcinomas (BLCs) present with extratumoral lymphovascular invasion, are highly metastatic, presumably through a hematogenous route, have augmented expression of CD44 oncoprotein and relatively low levels of retinoblastoma (Rb) tumor suppressor." (PMID 24324613, 2013). "The first solid tumour stem cells were identified in breast cancer, where it was demonstrated that a CD44+CD24- marker-bearing subpopulation could regenerate a tumour from as little as 100 cells, whereas tens of thousands of cells from the bulk population failed to do so." (PMID 23631621, 2013). "Approximately 15% of breast cancers are estrogen receptor (ER)-negative, high-grade and often basal-like breast cancer that are enriched in cells expressing putative stem cell markers CD44+/CD24− and over-expresses genes associated with embryonic stem cell gene signatures." (PMID 23536770, 2013). "However, the role of STAT3 signaling in ALDH+ and ALDH+/CD44+/CD24− subpopulations of breast cancer cells is unknown." (PMID 24376586, 2013). "Accordingly, CD44-positive BL-BCa cells may be more efficient in completing intravasation, consistent with the role of CD44 in promoting the spontaneous metastasis of breast cancer in vivo and the increased detection of CD44-enriched cells to disseminate to distant organs." (PMID 22621373, 2012). "It is therefore necessary to understand the reasons for CD44+/CD24- breast cancer cells in bone: whether CTCs are CD44+/CD24- CSCs that preferentially migrate and establish metastases, or if non-CD44+/CD24- CTCs are induced to the CD44+/CD24- phenotype in the bone marrow." (PMID 22934288, 2012). "Finally, they analyzed the miR-373 expression in breast cancer clinical specimens and found a significant up-regulation of miR-373 in 11 matched normal/tumor samples, which inversely correlated with CD44 expression, in particular in tumors exhibiting lymph node metastasis." (PMID 22408395, 2012). "Thus CD44 may present an important determinant of breast cancer progression in the setting of endocrine resistance." (PMID 23039365, 2012). "Moreover, this interaction could be abrogated through the depletion of CD44 expression using RNA interference and induced by the transfection of a CD44low breast cancer cell line with CD44 expression vectors." (PMID 22295241, 2012). "Notably, the bone marrow microenvironment is enriched in TGF-β, a cytokine that is well-known to induce EMT, and production of TGF-β by microenvironment stromal cells may be responsible for CD44+/CD24- breast cancer cells in bone." (PMID 22934288, 2012).
breast carcinoma (continued). "Additionally, the IL-6-induced CD44+ cells exhibited increased resistance to radiation, and reduced cell death after doxorubicin treatment compared with CD44− cells, which was consistent with the characteristics of breast cancer stem cells (BrCSCs) reported in previous studies." (PMID 22134360, 2012). "To verify these model predictions, we treated the MCF-7 cell line and primary breast cancer (BC) cells from 3 patient samples with different concentrations and dosing regimens of Dkk1, and evaluated subsequent formation of mammospheres (MS) and the mammary SC marker CD44+CD24lo." (PMID 21915302, 2011). "However, it has not been shown if the expression of specific CD44 isoforms is associated with CSCs or various breast cancer biomarkers and tumor subtypes." (PMID 21957977, 2011). "Hence, while the CIC enriched subset may be isolated from breast cancer cell lines by the CD markers CD44 and CD24, ALDH, or membrane labeling dye PKH26, obtaining pure cancer stem cell subsets remains a challenge in methodology." (PMID 21935375, 2011). "CD44+CD24-/low expression showed association with death due to breast cancer (p = 0.035) but not with age (p = 0.789), menopausal status (p = 0.131), clinical stage (p = 0.219), histological grade (p = 0.319), lymph node status (p = 0.895), recurrence (p = 1.000), or distant metastasis (p = 0.479)." (PMID 21824412, 2011). "Possibly this may be due to poor specificity of different CD44 antibodies, but also to small sample numbers and biased selection, particularly in breast cancer which is a heterogeneous disease consisting of several subtypes with different biology and clinical outcome." (PMID 21957977, 2011). "In addition to breast cancer tissue, CD44+/CD24−/low/ESA+ cells have also been isolated from breast cancer-derived cell lines with several of such cell lines containing a subset of CD44+/CD24−/low−/EAS+ cells possessing CIC properties such as the capacity for self-renewal." (PMID 21935375, 2011). "Work on breast cancer cell lines suggests that the radio resistance of the CD44+/CD24- subset of cells with stem-like characteristics might be related to increased activation of Notch, a molecule reported to protect normal and breast cancer cells against diverse apoptotic stimuli." (PMID 20426848, 2010). "However, there are no overlapping genes between our results and the gene signature identified by gene expression profiling of CD44+CD24- breast cancer stem-like cells; therefore, our findings should be validated in further studies, for example, analysis of stem cell marker expression." (PMID 20696077, 2010). "Separately, breast cancer stem cells, identified prospectively as tumor initiating cells when transplanted into immunodeficient mice, have been characterized by the surface expression phenotype CD44+/CD24−/low, also a presumed phenotype of normal breast epithelial stem or early progenitor cells." (PMID 19582160, 2009). "Altogether, our observations support the intriguing hypothesis that the CD44+CD24−/low cells (or at least a fraction of them) present within a primary breast cancer might reflect the propensity of malignant cells to undergo transdifferentiation and metastasize." (PMID 18682804, 2008). "We investigated whether breast cancer cells with the CD44+/CD24- phenotype possess three essential characteristics of cells with metastatic phenotype: expression of invasion/metastasis-associated genes; invasion; and homing and proliferation at sites of metastasis." (PMID 17062128, 2006). "Collectively, these findings underscore the potential of HIF-1α, CD44, and STC2 as both biomarkers and therapeutic targets in the management of breast cancer bone metastasis." (PMID 41596432, 2026). "CD44 is expressed in many isoforms, with the standard isoform being the most prevalent in MDA-MB-231 breast carcinoma cells." (PMID 40806710, 2025).
breast carcinoma (continued). "In breast cancer, the binding of LMW‐hyaluronan with CD44 and TLR2/4 promotes cell invasion, along with the activation of NF‐κB pathway and transcription and release of pro‐inflammatory cytokines such as ΤΝF‐α, IL‐1β, IL‐8, and IL‐12." (PMID 40542654, 2025). "A study on cancer stem-like traits revealed that, in MDA-MB-231 breast cancer cells, subpopulations with high CD147 surface expression show enhanced membrane localization of CD44, EGFR, MCT4, ABCB1, and ABCG2, highlighting their coordinated interactions." (PMID 41479915, 2025). "In breast cancer, LOXL2‐activated PEAR1 phosphorylation facilitates metastasis by maintaining CD44 stability." (PMID 41395115, 2025). "These points collectively warrant further investigation into the potential regulatory mechanisms involving CD44 and SLC1A2 in ET-resistant breast cancers." (PMID 40410608, 2025). "The pretreatment and posttreatment levels of CD44, CD24, miR590-3p, miR599, and miR399-3p in breast cancer patients." (PMID 40587726, 2025). "In breast cancer, elevated levels of IL-33 have been correlated with increased proliferation, immunosuppression, and upregulation of CSC markers such as CD44 and ALDH1, primarily through activation of the Wnt/β-catenin signaling pathway." (PMID 41373619, 2025). "High expression levels of Fib‐11 and CD74 were correlated with improved survival in breast cancer, whereas high SPP1 and CD44 expression predicted worse PDAC outcomes." (PMID 40357856, 2025). "For instance, in breast cancer cells, MARCH8 ubiquitinates STAT3 and CD44, suppressing tumor metastasis, while in hepatocellular carcinoma, MARCH8 induces degradation of PTEN thereby promoting malignancy." (PMID 41023307, 2025). "In breast cancer, cisplatin treatment of MCF-7 cells slightly increased the CSC-enriched CD44+/CD24− subpopulation, indicating potential CSC enrichment after therapy." (PMID 40733139, 2025). "We show that R-RAS2 regulates CD98/LAT1 transporter-mediated mTOR pathway activation and mediates CD44-dependent cancer cell migration and invasion, thus providing a mechanism by which R-RAS2 promotes breast cancer cell metastasis." (PMID 40221767, 2025). "The upregulated differentially expressed breast cancer stem cell markers included CD56/NCAM1, POU5F1, PROCR/CD201, ITGA6, and the downregulated were ESR1, PGR, HER2/ERBB2, ABCG2, CD44, CD24, EPCAM, and CDH1." (PMID 40690373, 2025). "The pre- and posttreatment expression levels of CD44, CD24, miR590-3p, miR599, and miR399-3p by pathologic response in ER + subtype of breast carcinoma." (PMID 40587726, 2025). "CD147KO THP-1 cells exhibited significantly enhanced migration towards MCP-1 and chemoattractants secreted by MDA-MB-231 breast cancer cells compared to wild-type (WT) THP-1 cells, while surface expression of the adhesion molecule CD44 remained unchanged." (PMID 41303343, 2025). "The pre- and posttreatment expression levels of CD44, CD24, miR590-3p, miR599, and miR399-3p by pathologic response in HER2+ subtype of breast carcinoma." (PMID 40587726, 2025). "In this study, we used CD44 as a biological readout to investigate the interplay between dormancy and stemness in HER2-amplified breast cancer cells." (PMID 40430044, 2025). "The pretreatment and posttreatment levels of CD44, CD24, miR590-3p, miR599, and miR399-3p in breast cancer subtypes." (PMID 40587726, 2025). "CD44 is an integral membrane protein used as a CSC marker in many cancers, including breast cancers." (PMID 40587726, 2025). "The prevalence of CD44+/CD24− and ALDH1+ BCSCs varies across the four molecular subtypes of breast cancer." (PMID 41373619, 2025). "Breast cancer cell lines, MDA-MB-231 (TNBC and CD44+) and MCF-7 (CD44-), were used as in vitro models to evaluate CD44 selectivity." (PMID 40468893, 2025). "For example, CD44 and ABCC5 are highly expressed in breast cancer with bone metastasis and can serve as potential markers for this metastatic site." (PMID 40500539, 2025).
breast carcinoma (continued). "Cancer cells residing in a partial EMT state were isolated from the basal-like breast cancer subtype based on CD104 (β4 integrin) (ITGB4) and CD44 cell surface expression." (PMID 40764669, 2025). "The correlation analysis of HA, CD44, BRCA1, and BRCA2 showed only one strong correlation, BRCA1 and BRCA2 in breast cancer (r = 0.7; p < 0.0001), while in the case of colorectal cancer this correlation was much weaker (r = 0.5; p = 0.02)." (PMID 41373491, 2025). "CD44, which is differentially expressed in highly metastatic versus low metastatic breast cancer cells, was shown to mediate the transfer of ezrin as cargo in EVs that also transfer MDR Pgp1 to low metastatic cells and confer therapeutic resistance." (PMID 39851567, 2025). "FGF13-AS1 expression is reduced in breast cancer tumors compared with adjacent healthy tissue and is correlated with unfavorable prognosis and a higher proportion of BCSC (CD44+/CD24−)." (PMID 41181715, 2025). "The HA-conjugated N-GQDs (HA-N-GQDs) are designed to bind alongside CD44, that is over-expressed on the surface of MCF-7 breast cancer cells, leading to enhanced fluorescence in these cells." (PMID 41304734, 2025). "The pre- and posttreatment expression levels of CD44, CD24, miR590-3p, miR599, and miR399-3p by pathologic response in TN subtype of breast carcinoma." (PMID 40587726, 2025). "In the TCGA breast cancer dataset, SDC1 expression was notably correlated with the stem cell biomarkers CD133, CD44, CD24, POU5F1, SMAD2, and NANOG at the transcriptional level." (PMID 41364407, 2025). "In breast cancer, interactions between CD147, CD44, hyaluronan, EGFR, and MCT regulate tumor invasiveness and lactate metabolism." (PMID 41479915, 2025). "Furthermore, evidence have been provided that CD44 exists in two different states, which differ in HA-binding affinity, i.e, active on human breast cancer cells, and inactive on normal cells, and it may shift from inactive to active conformation upon appropriate stimuli within the TME." (PMID 40342488, 2025). "The expression levels of cancer stem cell genes CD44, CD24, and related miRNAs miR590-3p, miR599, and miR399-3p were aimed to be investigated before and after neoadjuvant therapy in breast cancer patients in this cross-sectional observational study." (PMID 40587726, 2025). "Public data analysis from breast cancer patients revealed post-radiotherapy upregulation of the β-catenin pathway, with elevated CTNNB1, MYC, and CD44 expression, alongside reduced CDKN2A and CDH1 levels, supporting clinical relevance." (PMID 40657369, 2025). "The expression of CD44 and CD24 genes and miR590-3p, miR599, and miR399-3p was analyzed by qPCR in pre- and posttreatment biopsies from breast carcinoma patients." (PMID 40587726, 2025). "Moreover, CD44, a matrix glycoprotein and one of the major hyaluronan receptors, serves as an important marker for breast cancer stem cells (CSCs) and has been correlated with resistance against hormonal therapies and enhanced invasive potential in ERα+ breast cancer." (PMID 39285617, 2025). "These markers, such as CD44+/CD24−/low and ALDH+ in breast cancer or CD133 in glioblastoma, are critical for CSC identification and tumor initiation." (PMID 39941751, 2025). "This study investigates the molecular expression of selected CSC markers (CD44, CD24, miR590-3p, miR599, and miR339-3p) in breast carcinoma patients before and after neoadjuvant chemotherapy (NAC)." (PMID 40587726, 2025). "To investigate the effect of propofol and FOXO3 on breast cancer cell stemness, we analyzed the percentage of ESA+/CD44+/CD24-/low cells by flow cytometry." (PMID 39991565, 2025). "For example, in pancreatic cancer, CSCs are identified by combinations like CD133+/CXCR4+, CD24+/CD44+, and other profiles, while in breast cancer, they express CD24−/low/CD44+." (PMID 40422220, 2025).
breast carcinoma (continued). "The MCF-7 mammary cancer cell line only exhibited an increased expression of SOX2, whereas the MDA-MB231 cell line only exhibited an increased expression of CD44." (PMID 40362259, 2025). "Further bioinformatics analysis of breast cancer based on TCGA database and the in vitro and in vivo detection results showed that TSP50 can regulate the expression of key BCSC factors, such as CD44, ALDH1, NANOG and OCT4." (PMID 39030572, 2024). "Increased expression of HAS, CD44, and RHAMM creates a favourable condition for immune cell infiltration and cell proliferation in breast cancer." (PMID 38791985, 2024). "For example, PD-L1 expression is increased in CD44+ breast cancer stem cells, CD133+ colorectal cancer stem cells, and CD44+ head and neck squamous cell carcinoma (HNSCC) stem cells; VTCN1 expression is also elevated in CD133+ glioblastoma stem cells." (PMID 39184916, 2024). "In breast cancer MC1 xenograft models, MK-0752 reduced the CD44+/CD24− and ALDH+ CSC populations, and serial transplantation confirmed a reduction in tumorigenicity." (PMID 38612911, 2024). "It was found to inhibit proliferation and induce apoptosis of CSCs (CD44+CD24Low− and ALDH+) derived from the mammary breast cancer cell line MCF7 and of ALDH+CD133+ cancer stem-like cells from two high-grade serous ovarian cancer patients." (PMID 38659591, 2024). "Our previous work has demonstrated that stem-like breast cancer cells, defined as cells with high ALDH activity and CD44 expression, displayed enhanced metastatic potential and preferential metastasis to the lung." (PMID 38581619, 2024). "Breast cancer bone metastasis is thought to be significantly influenced by Runx2, which is regulated by OPN-αvβ3/CD44 axis." (PMID 39062100, 2024). "This study introduces novel CD44-targeted and redox-responsive nanoparticles (FNPs), proposed as doxorubicin (DOX) delivery devices for breast cancer." (PMID 39408889, 2024). "It has been reported that CD44+ and CD24 are the major CSC markers described for invasive breast cancer cells from cell lines." (PMID 38392969, 2024). "In the present investigation, we analyzed the role of miR-204 in the CSCs (CD44+/CD24−) isolated from MDA-MB-231 and Hs-578t breast cancer cell lines on VM and angiogenesis." (PMID 38392969, 2024). "It significantly blocks the expansion CSCs generated by breast cancer MCF7 cell line, as determined by reduced expression of CD44 and ALDH1, under anchorage-independent growth conditions and the mammosphere assay." (PMID 38659591, 2024). "For example, expression of CD44, CD24, and ALDH1A3 can quantify epithelial and mesenchymal stem cell states in breast cancer and normal breast tissue." (PMID 38915368, 2024). "Evidence suggests that breast cancer stem cells develop resistance through upregulation of stemness and chemo-evasion markers like SOX2, OCT4, NANOG, MDR1, and CD44, following chemotherapy." (PMID 39519572, 2024). "The cell surface markers CD44+/CD24- are widely used to identify and isolate CSCs from breast cancer, whereas CD44+/CD24-enriched CSCs have been found in mesenchymal TNBC." (PMID 39201646, 2024). "A significant decreased CD44+/CD24− CSC subpopulations and mammosphere formation were observed in breast cancer cells upon ropivacaine treatment." (PMID 38523299, 2024). "Real-time PCR analysis showed that SMS2 decreased CD24 transcription level but increased the transcription levels of stemness-related genes including CD44, ALDH, OCT 4 and SOX2 in breast cancer cells (P < 0.05)." (PMID 38285090, 2024). "Some biomarkers, which have been mentioned here, and researched for their clinical utility in locating and characterizing breast cancer include EGFR, HER2, ER, CD24, CD44, and CD47." (PMID 40051976, 2024). "Mice transplanted with CD24−/CD44+‐breast CSCs exhibited a significant increase in tumor size and weight as compared with that of CD24+‐breast cancer cells, suggesting the high tumorigenic potential of breast CSCs as compared to cancer cells." (PMID 38522013, 2024).